LINC02908 (long independently transcribed non-coding RNA 2908)
Synonyms: C9orf139; FLJ36268; FLJ42909
Gene: Long non-coding RNA gene on chromosome 9 (137,027,464 to 137,037,957, forward strand). Ensembl gene ENSG00000180539.
Diseases named in the same sentence as LINC02908 in open-access papers:
LINC02908 is named in the same sentence as 6 diseases in open-access papers, as found by Europe PMC text mining. Sharing a sentence is not in itself a finding about the gene and the disease. The quoted sentences say what the papers report.
herpes infection (1 paper, 2025). "Its involvement in paraspeckle formation could also be explored for broader antiviral strategies.LncRNAs, including LINC02693, C6orf223, TMEM132E-DT, and LINC02908, regulate gene expression, immune responses, and viral replication in herpes infection." (PMID 40144645, 2025).
LINC02908 also shares sentences with these, for which no sentence is quoted: pancreatic cancer (4 papers); acute myeloid leukemia (1); breast carcinoma (1); ovarian carcinoma (1); tumours (1).